CCDC62 (coiled-coil domain containing 62)
Description:
Nuclear receptor coactivator that can enhance preferentially estrogen receptors ESR1 and ESR2 transactivation. Also modulates progesterone/PGR, glucocorticoid/NR3C1 and androgen/AR receptors transactivation, although at lower level; little effect on vitamin D receptor/VDR. Required for normal spermiogenesis. It probably plays a role in acrosome formation (By similarity).
Synonyms: TSP-NY; FLJ40344; CT109; ERAP75; SPGF67
Tractability: PROTAC: ubiquitination databases record sites on it.
Gene: Protein-coding gene on chromosome 12 (122,774,526 to 122,827,528, forward strand). Ensembl gene ENSG00000130783.
Subcellular location: Cytoplasm; Nucleus; Cytoplasmic vesicle, secretory vesicle, acrosome
Subcellular location (Human Protein Atlas): Plasma membrane; Nucleoplasm
Gene Ontology:
Molecular function: nuclear estrogen receptor binding; protein binding; transcription coactivator activity
Biological process: cellular response to estradiol stimulus; estrogen receptor signaling pathway; positive regulation of transcription by RNA polymerase II; spermatid development
Cellular component: acrosomal vesicle; nucleoplasm; nucleus; microtubule organizing center; cytoplasm
Genetic constraint (gnomAD): Loss-of-function variants: 45 observed, 57 expected, observed/expected ratio (o/e) 0.79, 90% interval 0.62 to 1.01. The upper end of that interval is the gene's LOEUF score, 1.01, which puts it in group 4 of 6, group 1 being the genes least tolerant of losing a copy. Missense variants: 554 observed, 650.39 expected, observed/expected ratio (o/e) 0.85, 90% interval 0.79 to 0.91. Synonymous variants: 233 observed, 243.45 expected, observed/expected ratio (o/e) 0.96, 90% interval 0.86 to 1.07.
Homologues: Orthologues: chimpanzee CCDC62 (99% identical), macaque CCDC62 (96% identical), dog CCDC62 (83% identical), pig CCDC62 (82% identical), rat Ccdc62 (76% identical), mouse Ccdc62 (74% identical), guinea pig CCDC62 (73% identical), rabbit CCDC62 (72% identical), tropical clawed frog ccdc62 (30% identical).
Diseases named in the same sentence as CCDC62 in open-access papers:
CCDC62 is named in the same sentence as 13 diseases in open-access papers, as found by Europe PMC text mining. Sharing a sentence is not in itself a finding about the gene and the disease. The quoted sentences say what the papers report.
Parkinson disease (5 papers, 2012 to 2025). A progressive degenerative disorder of the central nervous system characterized by loss of dopamine producing neurons in the substantia nigra and the presence of Lewy bodies in the substantia nigra and locus coeruleus. "Parkinson disease risk alleles in Mapt (rs2942168) and Ccdc62 (rs12817488) loci were associated with global parkinsonism." (PMID 32997292, 2021). "The first large-scale meta-analysis of published genome-wide association studies (GWAS) in Parkinson’s disease (PD) identified 5 new genetic loci (ACMSD, STK39, MCCC1/LAMP3, SYT11, and CCDC62/HIP1R)." (PMID 24312176, 2013). "Interestingly, our results identified several loci that have been previously associated with the risk of Parkinson’s disease (e.g.: LRRK2, ITKB, CCDC62), but no loci overlapping with frontotemporal dementia in addition to the MAPT locus." (PMID 35589863, 2022).
Globozoospermia (4 papers, 2020 to 2024). Any structural anomaly of the acrosome resulting in a round sperm head. "The pathogenicity classification and function of the gene make the homozygous nonsense variant in CCDC62 the most likely cause of globozoospermia in this patient." (PMID 31985809, 2020). "We identified two likely pathogenic homozygous nonsense mutations, which most probably lead to a truncated protein (ZPBP; c.931C > T; p.(Gln311*)) or nonsense-mediated mRNA decay (CCDC62; c.442C > T; p.(Gln148*)), in genes previously known to cause globozoospermia when mutated in mice." (PMID 31985809, 2020). "In conclusion, according to the evidence reported so far, besides DPY19L2, other genes that might be confidently associated with globozoospermia in humans, and whose analysis might be recommended in clinical practice, are SPATA16, PICK1, ZPBP1, and CCDC62." (PMID 38790229, 2024). "CCDC62 contains coiled-coil domains similar to PICK1 and GOPC, whose knockout mouse models display also globozoospermia." (PMID 31985809, 2020).
prostate carcinoma (3 papers, 2013 to 2022). A carcinoma that arises from epithelial cells of the prostate gland. "CCDC62 is linked to estrogen receptor transactivation, cyclin D1 expression in prostate cancer cells, and antibodies to this protein develop in a variety of cancers." (PMID 24312176, 2013). "The CCDC62 gene plays a role in tumor progression of gastric and prostate cancers." (PMID 35936781, 2022).
fatty liver (1 paper, 2025). "In addition, its gene expression level significantly decreased after overfeeding, suggesting that CCDC62 may play an important role in alternative splicing-mediated regulation during the development of overfeeding-induced fatty liver." (PMID 41516281, 2025).
male infertility (1 paper, 2023). The inability of the male to effect fertilization of an ovum after a specified period of unprotected intercourse. "Knockout of Ccdc9, Ccdc38, Ccdc42, Ccdc62, Ccdc87 and Ccdc136 results in male infertility in mouse models because of defects in sperm flagella." (PMID 37601242, 2023).
cancer (2 papers, 2013 to 2016). A tumor composed of atypical neoplastic, often pleomorphic cells that invade other tissues. "Up to now, functional studies of CCDC62 remain poor, and are mainly associated with cancer." (PMID 27035708, 2016).
CCDC62 also shares sentences with these, for which no sentence is quoted: frontotemporal dementia (1 paper); macrozoospermia (1); neurological disorders (1); Parkinsonism (1); Prader-Willi syndrome (1); sterility (1); tumor (1).